TKT (transketolase)
Diseases named in the same sentence as TKT in open-access papers (continued):
Sharing a sentence is not in itself a finding about the gene and the disease.
TKT also shares sentences with these, for which no sentence is quoted: lymphoma (6 papers); viral infection (4); gastric carcinoma (3); Ataxia (2); neuropathy (2); osteosarcoma (2); parasitemia (2); sarcoidosis (2); thyroid cancer (2); acute kidney injury (1); adenocarcinoma (1); alcoholism (1); atherosclerosis (1); bacterial infections (1); bladder cancer (1); Brain atrophy (1); campylobacteriosis (1); cerebral infarction (1); colibacillosis (1); dermatitis (1); diabetic nephropathy (1); encephalitis (1); endothelial dysfunction (1); gastric adenocarcinoma (1); hearing loss (1); hematological malignancies (1); Hyperinsulinemia (1); hyperplasia (1); influenza (1); insulin-dependent diabetes mellitus (1).
A further 19 diseases each share a sentence with TKT in 1 paper.